ENSG00000287050 (novel transcript)
Gene: Long non-coding RNA gene on chromosome 6 (26,287,862 to 26,332,675, reverse strand). Ensembl gene ENSG00000287050.
Gene Ontology:
Molecular function: triplet codon-amino acid adaptor activity
Biological process: translation